CRP (C-reactive protein)
Diseases named in the same sentence as CRP in open-access papers (continued):
Sharing a sentence is not in itself a finding about the gene and the disease.
depression (continued). "It has been advocated that future clinical trials in depression should follow precision medicine principles by selecting a priori a subset of patients with elevated inflammatory markers, such as CRP, who most likely would respond to anti-inflammatory drugs." (PMID 34872404, 2021). "The lack of a significant correlation between brain TSPO binding and blood CRP concentration or body mass index poses questions about the interactions between central and peripheral immune responses in the pathogenesis of depression." (PMID 33515765, 2021). "Recent findings suggest that inflammation contributes to the emergence of depression, since elevated CRP predicts the subsequent development of depressive symptoms." (PMID 34764926, 2021). "General population studies demonstrate that about 30% of the individuals who were taking antidepressants or who were hospitalized for depression had increased levels (i.e., >3 mg/L) of C-reactive protein (CRP), a clinical marker of inflammation." (PMID 32873895, 2021). "Miller et, al., found that among healthy adults without any acute infectious disease or chronic medical illnesses, those who met clinical depression criteria had significantly higher levels of both CRP and IL-6." (PMID 32691611, 2021). "TNF antagonism seems to be particularly effective in patients with treatment-resistant depression, signs of inflammation (CRP > 5 mg/L) and elevated plasma lipids and cholesterols." (PMID 33653423, 2021). "In a study of African Americans recruited from the Washington, D.C. area, there was a stronger relationship between increased CRP levels and depression for those who experienced greater hostility and had lower educational attainment." (PMID 32691611, 2021). "In this study, CRP levels remained high in adolescents with depression and childhood adversity, even 6 months after the depressive symptoms improved." (PMID 34576215, 2021). "Further, baseline CRP levels have been reported to predict distinct treatment outcomes and influence antidepressant selection in patients with depression." (PMID 34943627, 2021). "From an inflammatory perspective, depression can be regarded as aa pro-inflammatory condition marked by the different inflammatory biomarkers such as interleukin IL-6, TNFα, and C reactive protein." (PMID 34045980, 2021). "In the analytic models adjusted for age, sex and baseline symptoms of depression, the odds of depressive symptoms during June/July 2020 increased 69% for high CRP and 29% for each unit increase in fibrinogen." (PMID 34887380, 2021). "Inflammatory cytokines, including interleukins (ILs) and C-reactive protein (CRP) that have been applied in our daily practice have been proposed to be related to depression and anxiety disorders." (PMID 34943627, 2021). "The regression model showed that a preoperative hs-CRP level > 2.02 mg/L was significantly correlated with postoperative depression in patients with ENS (odds ratio, 19.9)." (PMID 34943627, 2021). "A clinical study reported increased inflammation along with CRP elevation in patients with depression on tricyclic or tetracyclic antidepressants." (PMID 33809508, 2021). "Large meta-analyses report cross-sectional and longitudinal associations between inflammatory markers - such as C-Reactive Protein (CRP) and Interleukin 6 (IL-6) - and depression." (PMID 34135474, 2021). "On the other hand, Miller and Cole reported that the transition to depression in adolescents previously exposed to childhood adversity was accompanied by increased CRP levels." (PMID 34576215, 2021). "In bidirectional analyses, there was evidence of heterogeneity for bipolar disorder as exposure with sIL-2Rα, CRP, neutrophils and lymphocytes as outcomes, and major depression as exposure with CRP as outcome (all p<0.05)." (PMID 34280516, 2021). "Using CRP as a categorical variable, the adjusted OR for depression for participants in the top, compared with bottom, quintile of CRP was 1·29 (95% CI, 1·18–1·40)." (PMID 34505025, 2021).
depression (continued). "Based on univariate analysis, we observed that patients with severe anxiety, borderline abnormal or abnormal depression scores, low QoL, sleep disturbances, sarcopenia, malnutrition, and abnormal CRP (> 0.1 mg/dL) were more likely to report severe fatigue." (PMID 34315951, 2021). "CRP is an archetypal inflammatory marker and has been used most extensively as a measure of inflammation in depression." (PMID 34729541, 2021). "Meta-analyses of the literature concluded that peripheral blood IL-1β, IL-6, TNF, and C-reactive protein (CRP) are the most reliable inflammatory biomarkers in patients with depression." (PMID 34093252, 2021). "In this study, we explored the interaction between CRP and 114 gut microbiome-related traits and observed a significant interaction between them for depression and anxiety." (PMID 34481527, 2021). "Elevated peripheral C-reactive protein levels and depression symptoms were observed in patients with fibromyalgia or sciatica, while higher C-reactive protein levels correlated with greater depressive symptoms." (PMID 34526064, 2021). "Using MR analyses, we provide evidence that higher IL-6 activity could represent a potential causal factor increasing depression, while genetically predicted higher CRP concentrations appeared to potentially be protective for depression and anxiety, which contrasts findings for serum CRP." (PMID 34505025, 2021). "Elevated levels of CRP at baseline were predictive of depression at follow-up in the total sample (OR 1.58, 95% CI 1.10–2.26)." (PMID 33500534, 2021). "In patients with depression, the levels of CRP, IL-6, IL-12, and TNF-α are significantly elevated, indicating a pro-inflammatory state." (PMID 35087377, 2021). "A recent meta-analysis showed that vitamin D supplementation was followed by a significant reduction in depressive symptoms and CRP levels in patients with mental health problems (schizophrenia, depression, etc.)." (PMID 34201276, 2021). "Studies suggest that depression is associated with elevated levels of both pro-inflammatory and anti-inflammatory cytokines, e.g., IL-1β, IL-6, IFN-γ, TNF-α, and C-reactive protein (CRP)." (PMID 33920992, 2021). "Similar increases in basal ganglia Glu have also been reported in patients with major depression (MD) with increased endogenous inflammation, indexed by the acute phase reactant C-reactive protein (CRP)." (PMID 34482366, 2021). "Further analysis showed that the link between CRP/GE and depression is even more pronounced if both inflammation markers are simultaneously present." (PMID 34764926, 2021). "Our findings that levels of CRP and IL-6 are predictive of minocycline response in depression are consistent with existing evidence." (PMID 33504955, 2021). "Cohorts of patients with depression have increased blood concentrations of C-reactive protein (CRP) and pro-inflammatory cytokines compared to healthy controls." (PMID 34535766, 2021). "The multivariate logistic regression model further showed that age and a preoperative hs-CRP level > 2.02 mg/L were significantly correlated with postoperative depression status (p = 0.044 and 0.008, respectively)." (PMID 34943627, 2021). "This demonstrated a highly significant difference in the distribution of PD (right-shifted) in high CRP (> 3 mg/L) versus low CRP (< 3 mg/L) depression cases (Kolmogorov-Smirnov test, P < 6.4 × 10−7) and between high CRP depresssed cases and controls." (PMID 34535766, 2021). "A meta-analysis demonstrated that there was a significant correlation between depression and C-reactive protein (CRP) and IL-6 in children and adolescents." (PMID 34875999, 2021). "The MR-PRESSO Global Test additionally suggested the potential of horizontal pleiotropy affecting schizophrenia with IL-12 and CRP as outcomes, bipolar disorder with CRP as outcome, and major depression with CRP as outcome (p<0.05)." (PMID 34280516, 2021).
depression (continued). "Simple slopes models indicate the consistent pattern of increased ORs for depression at the elevated CRP cut-point compared to the reference cut-point." (PMID 34639705, 2021). "Another study investigated neuroinflammation in individuals with late-life depression and reported elevated CRP levels and hippocampal structural reductions." (PMID 35008730, 2021). "Another study showed that the levels of fasting CRP were significantly increased in remitted women with major depressive disorder (MDD) versus controls." (PMID 34421539, 2021). "We are now conducting a proof-of-concept RCT of tocilizumab for depressed patients with elevated CRP and somatic symptoms of depression." (PMID 34280516, 2021). "There is a study showing that depression is positively correlated with interleukin- (IL-) 1, C-reactive protein (CRP), and IL-6 in community and clinical samples." (PMID 34712368, 2021). "This emphasizes the importance of screening for and diagnosing depression in those with serum UA and hs-CRP level imbalances." (PMID 34650110, 2021). "For example, studies have found that the concentrations of IL-6 and C-reactive protein are increased in serum or plasma of depressed individuals, and are significantly correlated with the severity of depression." (PMID 34531719, 2021). "Self-reported e-cigarette use, depression survey responses, and serologic CRP data from the nationally representative National Health and Nutrition Examination Survey (NHANES) were used to investigate these associations." (PMID 34639705, 2021). "In summary, our results support the significant effect of interaction between CRP and gut microbiome on the risks of anxiety and depression, and identified several candidate gut microbiomes for them." (PMID 34481527, 2021). "Findings on depression in patients who displayed increased levels of peripheral inflammatory factors such as IL-6, CRP, and TNF-α can confirm this." (PMID 34942914, 2021). "The findings demonstrated that hs-CRP mediated the influence of depression symptoms on central obesity in White young adults." (PMID 34065158, 2021). "Our results support the significant effect of interaction between CRP and gut microbiome on the risks of anxiety and depression, and identified several candidate gut microbiomes for them." (PMID 34481527, 2021). "In this study, the hs-CRP level decreased significantly one year after surgical treatment for ENS patients with preoperative depression or anxiety." (PMID 34943627, 2021). "The β adjusted for baseline depression, age and sex (β = 0.23, 95% CI 0.10–0.36, p < 0.001) was 0.14 (95% CI 0.01–0.27, p = 0.034) in the fully adjusted CRP model." (PMID 34887380, 2021). "Hs-CRP level seems to be a feasible predictor of surgical outcome regarding improved depression in patients with ENS." (PMID 34943627, 2021). "Two meta-analyses showed reliably higher levels of inflammatory markers in depression, namely IL-1β, IL-6, C-reactive protein (CRP), and TNF-α." (PMID 34975571, 2021). "Age, neurological deficits, cognitive dysfunction, degree of depression, hs-CRP, and ESR differed significantly between the two groups." (PMID 34828631, 2021). "Using the categorical outcomes, MR analyses also showed that increased genetically-predicted CRP was associated with lower risk for probable GAD, but point estimates for probable depression were close to one." (PMID 34505025, 2021). "A high level of interleukin-6 (IL-6) was predominantly observed in mania, tumor necrosis factor-α (TNF-α) was elevated in both depression and mania and C-reactive protein (CRP) level was even increased in euthymia." (PMID 34381386, 2021). "Separately, depressive symptoms are associated with pro-inflammatory processes, suggesting the utility of inflammatory proteins such as CRP as a potential systemic biomarker of major depressive disorders." (PMID 34639705, 2021).
depression (continued). "It is well established that patients with depression and anxiety have higher plasma levels of C-reactive protein and proinflammatory cytokines (e.g., TNFa, IL-1a, IL-1b, IL-4, IL-5, IL-6, IL-12, and interferon)." (PMID 33802143, 2021). "More recent reviews resume that IL-1 ß, IL-6, TNF-α, and C-reactive protein (CRP) are the most consistently identified biomarkers of inflammation in depression." (PMID 34204400, 2021). "Especially with respect to CRP, it was suggested that the relationship with depression symptoms only applies to men44,45." (PMID 33500534, 2021). "Relatively consistent findings showed an increase in several cytokines, including interleukin-6 (IL-6), interleukin-1 (IL-1), tumor necrosis factor-alpha (TNF-α), and C-reactive protein (CRP) in patients with depressive disorder versus healthy controls (HCs)." (PMID 34576215, 2021). "Childhood risk factors associated with at least 2 of 3 opioid outcomes included tobacco use, depressive disorders, conduct disorders, having peers exhibiting social deviance, parents with legal involvement, and elevated systemic inflammation (high CRP level)." (PMID 33369615, 2021). "This study was conducted to anticipate of high-sensitivity-CRP (hs-CRP) effect on post-MI depression disorder." (PMID 35434159, 2021). "Patients with a depressive disorder have been shown to have increased peripheral blood levels of CRP." (PMID 33672126, 2021). "Using a general population-based birth cohort study, we report that a notable proportion of young adults with current depression have evidence of raised CRP." (PMID 32339985, 2020). "A feature of most existing epidemiological studies of depression is that they used a one-off measure of CRP to gauge inflammation." (PMID 31707310, 2020). "The longitudinal measurement model including DS-PGS, CRP, symptom-specific dimensions of depression and covariates showed a good model fit (RMSA = 0.018, CFI = 0.972, Pearson χ2 < 0.0001)." (PMID 32398645, 2020). "The result showed that omega 3 and polyunsaturated fatty acids had protective effects for depression in men, and CRP was the marker that was significantly affected." (PMID 32131552, 2020). "All patients were evaluated using Hospital Anxiety and Depression Scale, CRP and erythrocyte sedimentation rate, at baseline and after 6 months." (PMID 33235810, 2020). "Some of the inflammatory markers elevated in depression, including CRP and IL-12, show reduced variability in patients with depression, therefore supporting greater homogeneity in terms of an inflammatory phenotype in depression." (PMID 32113908, 2020). "In this study we find that mean-scaled variability of CRP and of a number of other immune markers is either reduced or unchanged in patients with depression as compared to healthy controls." (PMID 32113908, 2020). "Out of 215 cases of current depression, 135 (62.7 %) had CRP <1 mg/L, 57 (26.5 %) had CRP 1−3 mg/L, and 23 (10.7 %) had CRP >3 mg/L." (PMID 32339985, 2020). "There was a significant improvement in depression scores, in addition there were significant improvements in insulin and CRP values and in oxidative stress parameters in the active treatment group compared to the placebo group." (PMID 32858844, 2020). "Elevated CRP along with other peripheral blood markers of inflammation have been found to predict development of depression and resistance to antidepressant therapy." (PMID 33213019, 2020). "Our meta-analysis finds evidence that mean-scaled variability, measured as CVR, is reduced in patients with depression for CRP, IL-12 and sIL-2R, while it is unchanged for IL-3, IL-6, IL-18 and TNF α." (PMID 32113908, 2020). "One study investigated hazard ratio and showed that CRP significantly predicted earlier time to onset or relapse/recurrence of depression." (PMID 31745238, 2020).
depression (continued). "We suggested increased inflammation as shared potential pathophysiological mechanism, as higher levels of inflammation (like C-reactive protein, CRP) are known associates of depression and anxiety." (PMID 34589860, 2020). "A linear association was observed between hepcidin levels and RLSQoL scores after adjusting confounding factors such as age, sex, difference of CRP, depression, anxiety and insomnia scores after treatment (β = 0.002, 95% CI 0.00–7.01, p = 0.044)." (PMID 33419264, 2020). "Clinically, elevated levels of CRP and IL-6 were observed in patients with depression when compared to healthy subjects and were associated with cognitive symptoms in such patients." (PMID 32922295, 2020). "Neither bivariate effect was significant, however there was a larger effect of CRP on anxiety as compared to depression." (PMID 32272662, 2020). "Whilst we included a relatively large overall sample, the numbers of participants with evidence of raised CRP and depression was relatively small." (PMID 32339985, 2020). "Several studies have shown increased levels of TNF-α, IL-6, and C-reactive protein (CRP) in patients with depression." (PMID 33343332, 2020). "CRP is an acute phase protein which has been studied extensively in depression and shown to be elevated in acutely unwell patients compared with controls in several meta-analyses." (PMID 31707310, 2020). "This study adds to the existing evidence by showing that increasing CRP levels between adolescence and young-adulthood are associated with a subsequent ICD-10 diagnosis of moderate/severe depression in young-adulthood at age 18 years." (PMID 31707310, 2020). "This is important because discrimination has the potential to result in elevation of primary stress mediators such as heart rate and secondary outcomes such as blood pressure, HBA1c, waist circumference, and C-reactive protein, leading to depression." (PMID 33354627, 2020). "The inflammatory response was enriched in the depression/anxiety module: c-reactive protein levels have been known to predict the outcome of antidepressant treatment and disease severity." (PMID 32398742, 2020). "The majority of studies have demonstrated that CRP levels are elevated in depression, although no causal relationship has been established between an enhanced CRP concentration and depression." (PMID 33255237, 2020). "Apart from being associated with depression, levels of IL6 along with IL1 and CRP have been shown to be increased in patients with cognitive impairment and in obese persons, respectively." (PMID 32781663, 2020). "Results showed that notwithstanding evidence of higher levels in all three phases when compared with healthy subjects, CRP rises more in the manic stage compared to depression and euthymia in BD." (PMID 32174850, 2020). "Out of 2932 participants with data on CRP and depression at age 18 years, 215 met ICD-10 criteria for current depressive episode (7.3 %)." (PMID 32339985, 2020). "Approaches such as stratifying patients based on a marker such as CRP, as has been done in depression, should be considered in treatment trials in patients with schizophrenia." (PMID 32153436, 2020). "Quality of life (QOL), depression and anxiety for assessment of psychosocial status of patients, and quantitative CRP were evaluated as secondary endpoints." (PMID 32404169, 2020). "Using the odds of possible depression (CES-D score ≥ 16) as outcome yielded similar results, although BASFI remained associated with possible depression, also after adjustment for CRP (models 4A–4D)." (PMID 32993799, 2020). "CRP and ESR, considered as independent risk factors for coronary artery disease and markers for systemic inflammation, are reported to be increased in depression." (PMID 33235810, 2020). "IL-1, IL-6, IL-1β, TNF-α, and CRP are considered markers of the initiation, relapse, and progression of depression." (PMID 32922295, 2020).